RARRES1 (retinoic acid receptor responder 1)
Diseases named in the same sentence as RARRES1 in open-access papers (continued):
Sharing a sentence is not in itself a finding about the gene and the disease.
tumor (41 papers, 2011 to 2025). "Univariate Cox regression analysis showed that tumor stage (T, N, M), patient age, ulceration, Clark level, Breslow depth, and RARRES1 expression were associated with survival." (PMID 38898266, 2024). "In our study, we conducted GO, KEGG, and GSEA enrichment analysis, which revealed a significant association between RARRES1 expression and the tumor immune microenvironment, cell cycle regulation, migration, apoptosis, autophagy, and oxidative damage." (PMID 38898266, 2024). "Collectively, although rarely mutated in cancers, these data support a role for RARRES1 as a tumor suppressor." (PMID 35541897, 2022). "By univariate survival analysis, the T classification, grade, stage, necrosis and size of tumours as well as the RARRES1 expression are significantly associated with tumour progression (all p < 0.001)." (PMID 32307444, 2020). "Angiogenesis is an important hallmark of tumor progression and our data showed that RARRES1 negatively modulates angiogenesis." (PMID 28678839, 2017). "Loss of RARRES1 in multiple tumor types, its role in stem cell differentiation and in cell survival indicates that the RARRES1/CCP2 axis could be a candidate for therapeutic intervention." (PMID 30899431, 2019). "For example, RARRES1 has been reported to promote apoptosis in renal podocytes and various tumor cells." (PMID 41178994, 2025). "Transwell assays and evaluation of EMT markers also demonstrated the tumor suppressor effect of RARRES1 on HCC cell lines, and its positive role in enhancing cell sensitivity to lenvatinib." (PMID 38388961, 2024). "In conclusion, these data show that RARRES1 exerts a tumor suppressor effect on HCC cell migration and EMT, and high RARRES1 expression acts synergistically with lenvatinib in HCC." (PMID 38388961, 2024). "RARRES1 overexpression or lenvatinib treatment alone both exhibited anti-tumor effects in Huh7 xenografts." (PMID 38388961, 2024). "Comprehensive functional experiments would contribute to understanding the detailed role of RARRES1 in the interactions between tumor cells and TME." (PMID 38533207, 2024). "Our findings highlighted that RARRES1 can inhibit HCC progression and regulate HCC sensitivity to lenvatinib by interacting SPINK2, representing a new tumor suppressor RARRES1/SPINK2 axis in HCC that modulates sensitivity to lenvatinib." (PMID 38388961, 2024). "Functional analysis showed that ectopic RARRES1 expression decreased HCC progression in vitro and in vivo, as well as improving tumor sensitivity to lenvatinib, while RARRES1 silencing increased HCC cell proliferation and migration." (PMID 38388961, 2024). "Our data reveal a new RARRES1 /SPINK2 axis with a tumor suppressor role in HCC, which decreased cell proliferation and migration and improve HCC cell sensitivity to lenvatinib." (PMID 38388961, 2024). "The expression of RARRES1 was significantly lower in the tumor grade 1 subgroup than in the normal subgroup and the tumor grade 2/3/4 subgroup (P<0.001)." (PMID 36353618, 2022). "In our vitro experiments, we showed that RARRES1 exerts anti-tumor effect on tumor cells through macrophages." (PMID 36353618, 2022). "This dramatic phenotype validates RARRES1 as a tumor suppressor in vivo and is consistent in two independently derived strains of mice." (PMID 35541897, 2022). "Research has shown that RARRES1 inhibits tumor cell proliferation or invasion and induces apoptosis of tumor cells." (PMID 36353618, 2022). "To analyze RARRES1 expression in subgroups, we divided KIRC patients stratified by RARRES1 expression into subgroups based on age, race, sex, pathological grade, and tumor stage." (PMID 36353618, 2022). "RARRES1 (retinoic acid receptor responder 1) is one of the common methylated loci in several cancers and is believed to be a putative tumor suppressor gene." (PMID 36424614, 2022).
tumor (continued). "My own laboratory has identified RARRES1 as a transcript repressed in the tumor-initiating population of prostate epithelial cells but upregulated in the tissue, restoring the population of (normal) basal transit amplifying cells." (PMID 33477370, 2021). "High RARRES1 expression was correlated with poor median survival of patients with inflammatory BRCA, while cell proliferation and tumor growth assays showed that RARRES1 was a tumor suppressor in triple-negative BRCA cell lines." (PMID 35047378, 2021). "Just like SFRP4, RARRES1 is downregulated in the final stage, related to the fact that it has been suggested as a tumor suppressor." (PMID 34283835, 2021). "Most interesting were the 4 genes that function as tumor suppressors: C10orf90, RARRES1, DMBT1, and SCGB3A1." (PMID 34769520, 2021). "The vast majority of conventional RCC displayed RARRES1 expression at the membrane of tumour cells, which corresponds to its position in proximal tubular cells." (PMID 32307444, 2020). "On the other hand, the membranous expression of RARRES1 at the surface of tumour cells marked the large group of patients (454 of 691) with excellent disease outcome." (PMID 32307444, 2020). "No expression was detected in 106 conventional RCC, whereas 131 tumours showed exclusively cytoplasmic RARRES1 expression." (PMID 32307444, 2020). "Out of 454 conventional RCC with membranous RARRES1 expression, 110 tumours showed AGBL2-positive staining as well." (PMID 32307444, 2020). "The 344 RARRES1 membrane-positive and AGBL2-negative tumours displayed identical Kaplan–Meier curve as it was seen for membranous RARRES1 alone." (PMID 32307444, 2020). "Within this group, 110 tumours displayed a strong cytoplasmic AGBL2 expression in addition to membranous RARRES1 expression." (PMID 32307444, 2020). "The vast majority of AGBL2-positive cases occurred in the group of tumours with RARRES1 membrane positivity." (PMID 32307444, 2020). "We report that RARRES1 expression inhibits the phosphorylated form of p38MAPK and also reduces its kinetic activity indicating possible mechanisms of tumor suppression and autophagy induction by RARRES1." (PMID 28678839, 2017). "Overall this study reports the molecular players that RARRES1 modulates to serve as a tumor suppressor molecule." (PMID 28678839, 2017). "Taking the role of RARRES1 as a tumor suppressor with a high methylation pattern in a variety of cancer types into consideration, we predicted that the RARRES1 expression matched promoter methylation in placental tissues and cell lines." (PMID 29169400, 2017). "Epigenetic silencing of RARRES1 expression and its effect on tumor cell invasion, proliferation and survival further underscored its tumor suppressive properties." (PMID 29169400, 2017). "Determining the molecular mechanisms that mediate the tumor suppressor role of RARRES1 in PCa is the focus of our study." (PMID 28678839, 2017). "We performed proteomic analyses with tandem mass tag (TMT) mass spectrometry using the three TNBC cell lines where RARRES1 suppresses cell proliferation and tumor growth (MDA-MB-231, MDA-MB-468, and HCC1937) to identify functional effects and associations." (PMID 27286452, 2016). "This is consistent with previous findings that AXL stabilization is an oncogenic mechanism for RARRES1, and with our own findings that RARRES1 is tumor suppressive in TNBC." (PMID 27286452, 2016). "In contrast, in this study we identified RARRES1 as a tumor suppressor in TNBCs, and highly expressed specifically within the basal-like subtype." (PMID 27286452, 2016). "The lack of changes to AXL and tubulin stability suggested the existence of other mechanisms by which RARRES1 acts as a tumor suppressor in TNBC." (PMID 27286452, 2016). "The RA receptor responder protein 1 (RARRES1) has also been identified as either suppressing or promoting tumor growth, depending on the study." (PMID 27286452, 2016).
tumor (continued). "For the first time, our preceding report, as well as current study, depicted a likelihood that tumor suppressor locus, RARRES1, was progressively methylated prior to undergoing epigenetic silencing." (PMID 22615834, 2012). "Its role of attenuating invasion agreed with data generated from clinical specimens revealing that RARRES1 was generally downregulated in metastatic lymph nodes compared to the tumor cores." (PMID 22615834, 2012). "We also revealed the tumor suppressive roles exerted by RARRES1 in part by promoting breast epithelial cell death and by impeding cell invasion that is an important property for metastatic spread." (PMID 22615834, 2012). "Collectively, our findings delineated multiple molecular perturbations are responsible for epigenetic silencing of RARRES1, in the light of the tumor microenvironmental effect, DNA methylation, CTCF binding, as well as histone modifications." (PMID 22615834, 2012). "Lxn has about 30% sequence homology, but much greater structural homology, with tazarotene-induced gene 1 (TIG1) (or retinoic acid receptor responder 1, RARRES1), whose expression was down-regulated in an extensive list of tumor types in humans." (PMID 23028717, 2012). "Xenograft tumor experiments were conducted to assess the in vivo effects of RARRES1." (PMID 38898266, 2024). "The anti-tumor activity of RARRES1 and lenvatinib against HCC was next examined in vivo." (PMID 38388961, 2024). "Research has shown that RARRES1 demonstrates anti-tumor effects in various cancer types." (PMID 38898266, 2024). "In the mouse xenograft model, RARRES1 overexpression also suppressed SKCM tumor growth." (PMID 38898266, 2024). "RARRES1 was found to be weakly expressed in the tumor tissues of SKCM." (PMID 38898266, 2024). "However, our present study demonstrated that the promoter region of RARRES1 in tumor was hypomethylated in comparison with surrounded normal tissue." (PMID 38421457, 2024). "Enrichment analysis suggested that RARRES1 may function as a tumor-suppressive factor by regulating various aspects of immune cell infiltration, proliferation, migration, apoptosis, and autophagy." (PMID 38898266, 2024). "It is interesting to note that a significant number of mRNAs from the signatures of genes suppressed during EMT, including FOXA1, DSC3, RARRES1, PTEN, and RARRES1, have characteristics of tumor suppressors, including inhibiting hypoxia, tumor cell proliferation, and tumor cell invasion." (PMID 36980175, 2023). "Previous studies indicated that RARRES1 has tumor suppressor characteristics." (PMID 35541897, 2022). "But the tumor microenvironment is complex, the tumor suppressor effects of RARRES1 may fail to counteract malignant tumor." (PMID 36353618, 2022). "In addition, the RARRES1 expression level was significantly lower in the tumor grade 2 and 3 subgroups than in the tumor grade 4 subgroup." (PMID 36353618, 2022). "RARRES1 is a tumor suppressor protein, and its expression is suppressed in various tumor cells." (PMID 36353618, 2022). "Previous research on RARRES1 indicated that it acted as a tumor suppressor in multiple cancers." (PMID 35541897, 2022). "We sought to determine the mechanism by which RARRES1 exerts a tumor-suppressive effect in KIRC." (PMID 36353618, 2022). "Whilst a regenerative RA response is marked strongly by RARRES1 upregulation, regrowth of the tumour component is less likely to be marked by increased RARRES1 expression, due to the uniformly low levels of RARRES1 detectable in most cancer cell types, including prostate." (PMID 33477370, 2021). "Kaplan–Meier analysis and Cox proportional regression model revealed that cytoplasmic expression of RARRES1 or lack of its expression are significantly associated with tumour progression predicting a five times higher risk for postoperative tumour relapse." (PMID 32307444, 2020).
tumor (continued). "Our observation suggests that RARRES1 may execute distinct biological functions in the same type of tumour depending on its subcellular localisation and co-expression with AGBL2." (PMID 32307444, 2020). "RARRES1 and AGBL2 expression defines groups of patients at low and high risk of tumour progression and may direct an active surveillance to detect metastasis as early as possible and to apply adjuvant therapy." (PMID 32307444, 2020). "Interestingly, subtype analysis revealed differential RARRES1 expression for more aggressive tumor phenotypes." (PMID 30557378, 2018). "Since FOXO1 can modulate the synthesis of antioxidant enzymes and it is well known that production of oxidative stress positively regulates tumor growth, we sought to determine if RARRES1 expression could modulate this phenomenon." (PMID 28678839, 2017). "Retinoic Acid Receptor Responder (RARRES1)/ Tazarotene-induced gene-1 (TIG-1) is a putative tumor suppressor gene that exerts its tumor suppressor function via unknown mechanisms." (PMID 28678839, 2017). "Based on our analysis, we hypothesize that RARRES1 might exert tumor suppressive functions in multiple cellular processes (e.g. cell cycle regulation, adhesion, invasion and apoptosis)." (PMID 29169400, 2017). "In particular, RARRES1 is an RA-inducible tumor suppressor gene." (PMID 27286452, 2016). "Our characterization of the RARRES1 gene offers an example of a subtype-specific tumor suppressor that may be useful as a biomarker in subtype-specific therapies." (PMID 27286452, 2016). "Cell proliferation and tumor growth assays reveal that RARRES1 is a tumor suppressor in TNBC." (PMID 27286452, 2016). "RARRES1 has been reported to have tumor suppressor function in a number of cancer types." (PMID 27286452, 2016). "RARRES1 is a retinoic acid receptor that acts as a vital tumor suppressor gene." (PMID 23922792, 2013). "Other than inhibiting tumorigenesis and hampering invasive properties of prostate cancer, increasing lines of evidence have indicated RARRES1 as an important tumor suppressor gene by regulating versatile cellular processes like cell proliferation, differentiation, and survival." (PMID 22615834, 2012). "Moreover, RARRES1 restoration not only impeded cell invasion but also promoted death induced by chemotherapeutic agents, denoting its tumor suppressive effect." (PMID 22615834, 2012). "The tazarotene-induced gene 1 (TIG1) gene, also known as retinoic acid receptor responder 1 (RARRES1) gene, may be a tumor suppressor." (PMID 22126303, 2011). "Nonetheless, RARRES1 might have a promotive effect on cancer development in specific tumor types." (PMID 38898266, 2024). "Importantly, RARRES1 overexpression combined with lenvatinib could significantly reduce tumor size than RARRES1 overexpression or Lenvatinib alone." (PMID 38388961, 2024). "However, the only gene whose expression was increased in all three transcriptional studies was retinoic acid responder 1 gene (RARRES1)—a known tumor suppressor gene in prostate, whose expression is positively regulated by retinoic acid in differentiating normal skin epithelium." (PMID 33477370, 2021). "Based on its localization in the human placenta, we have previously hypothesized that RARRES1, as a tumor-suppressor gene, might slow down invasion and migration of EVTs in terminal placentas and that it might regulate proliferation, syncytialization, and apoptosis of villous trophoblasts." (PMID 31905805, 2019). "We sought to determine the mechanism by which RARRES1 may function as a tumor suppressor in PCa." (PMID 28678839, 2017). "The expression of FBN1, RARRES1, and TIMP3 was positively correlated with multiple tumor-related pathways." (PMID 36424614, 2022). "The four combinations of RARRES1 and AGBL2 expression were significantly correlated with tumour size, grade, necrosis, T stadium and stage as well (Pearson Chi-square test, p < 0.001)." (PMID 32307444, 2020).
tumor (continued). "Retinoic acid receptor responder 1 (RARRES1) is a retinoid regulated gene, which is accounted as a tumor suppress gene and lost in many cancer cells." (PMID 23951052, 2013). "Tumors with a poor response to chemotherapy, i.e. less than 50% reduction in volume during preoperative chemotherapy, showed lower expression of RARRES1 and RARRES3 compared to tumors with a strong decrease in tumor volume." (PMID 22067876, 2011). "While RARRES1 is epigenetically silenced in many cancers, in vivo validation of RARRES1 as a tumor suppressor was lacking." (PMID 35541897, 2022). "Significantly, Rarres1 knockout affects CCP2 dependent tubulin glutamylation and increased bio-energetic capacity in mouse embryonic fibroblasts, but not in B cells, suggesting that RARRES1 is acting within the tumor microenvironmental niche as well." (PMID 35541897, 2022). "According to TIMER, a web tool for analyzing immune cell infiltration in TCGA data, we discovered that RARRES1 expression had a negative correlation with tumor purity in KIRC and strong positive correlations with the infiltration of B cells and macrophages." (PMID 36353618, 2022). "Of the group of 237 RARRES1-negative or cytoplasmic positive tumours, 69 showed AGBL2 positivity, whereas 168 ones were negative for AGBL2." (PMID 32307444, 2020). "In tumour biopsies, we detected either a membranous or cytoplasmic RARRES1 expression or no expression." (PMID 32307444, 2020). "A small group of seven patients with AGBL2-positive and RARRES1-negative tumour displayed a shortest survival by Kaplan–Meier curve estimation (data not shown)." (PMID 32307444, 2020). "Using multivariate analysis, only tumour necrosis (p = 0.017) and combination of RARRES1 cytoplasmic/negative and AGBL2-positive/negative immune reaction showed a significant correlation with survival rates." (PMID 32307444, 2020). "Cellular mechanisms via which RARRES1 exerts its tumor suppressor function have not been elucidated." (PMID 28678839, 2017). "Together, these results suggest that RARRES1 has a tumor suppressing role in TNBC regardless of molecular subtype." (PMID 27286452, 2016). "Tumor volume and weight of mammary fat pad-implanted MDA-MB-231 and MDA-MB-468 cells were significantly increased upon knockdown of RARRES1." (PMID 27286452, 2016). "In addition, RARRES1 expression was not related to tumor stage of TNBC." (PMID 38533207, 2024). "However, in vivo evidence of RARRES1 acting as tumor suppressor was lacking." (PMID 35541897, 2022). "With all probability, the lack of RARRES1 inhibitor function allows the catalysation of α-tubulin detyrosination by AGBL2 and promotion of tumour progression." (PMID 32307444, 2020). "In addition, we defined genes being expressed by all three MYC tumor groups, but absent in SHH tumors (e.g., Ogn, Tpm2, and Rarres1)." (PMID 35318328, 2022).